LIF (LIF interleukin 6 family cytokine)
Diseases named in the same sentence as LIF in open-access papers (continued):
Sharing a sentence is not in itself a finding about the gene and the disease.
acute liver failure (1 paper, 2019). Rapid deterioration of liver function causing encephalopathy and coagulopathy. "In contrast, levels of HGF, LIF, M-SCF, VCAM, and ICAM1 were highest for acute liver failure (ALF) and lowest for tumor patients, indicating that tissue damage plays the largest pathophysiological role in patients with ALF." (PMID 30740106, 2019).
acute pancreatitis (1 paper, 2023). An acute inflammatory process that leads to necrosis of the pancreatic parenchyma. "Some authors reported better usefulness in assessing interleukin-6 (IL-6) serum levels in differentiating PC patients from chronic or acute pancreatitis, or recently, leukemia inhibitory factor (LIF) was reported to be a promising serum biomarker of pancreatic malignancy." (PMID 37906289, 2023).
alcoholic liver diseases (1 paper, 2004). A disorder caused by damage to the liver parenchyma due to alcohol consumption. "Especially interesting is the demonstration that LIF can stimulate the adhesion of neutrophils to endothelial cells; indeed, neutrophils are involved in the pathogenesis of liver diseases such as alcoholic liver disease." (PMID 15566573, 2004).
allergic asthma (1 paper, 2025). A asthma with a basis in a pathological type I hypersensitivity reaction. "emu-miR-10a-5p intervention inhibited LIF and JAK1–STAT3 signaling in the lungs of mice with allergic asthma." (PMID 40496853, 2025). "In this study, we found that EVs and emu-miR-10a-5p secreted by E. multilocularis act on the JAK1–STAT3 signaling pathway by targeting and binding to leukemia inhibitory factor (LIF), inhibiting M2a macrophage polarization and thereby alleviating OVA-induced allergic asthma." (PMID 40496853, 2025).
anorexia nervosa (1 paper, 2022). A disorder most often seen in adolescent females characterized by a refusal to maintain a minimally normal body weight, an intense fear of gaining weight, a disturbance in body image, and, in postmenarcheal females, the development of amenorrhea. "We summarize the main roles of LIF in the development of cancer cachexia, including promoting fat loss, inducing skeletal muscle atrophy and causing anorexia nervosa." (PMID 35740622, 2022). "In addition, blocking LIF to improve anorexia nervosa and fat loss should be an effective treatment." (PMID 35740622, 2022).
Autoimmunity (1 paper, 2024). The occurrence of an immune reaction against the organism's own cells or tissues. "The OSM and LIF genes, members of the IL-6-related family, are pleiotropic cytokines with similar genetic structures and physiological functions that play important roles in chronic inflammation, autoimmunity, infectious diseases, and cancer." (PMID 38591204, 2024).
B-cell CLL (1 paper, 2017). "Interestingly, RNAi-mediated ablation of BCL3 (B-cell CLL/Lymphoma 3) expression in activated fibroblasts, leads to a strong decrease of ICAM-1 expression both in LIF-activated fibroblasts and in CAF (data not shown)." (PMID 27901489, 2017).
bile duct cancer (1 paper, 2023). "Importantly, human pancreatic, stomach, brain, and bile duct cancer all have overexpression of both IL-1α and LIF relative to normal tissue while having only minor changes in G-CSF." (PMID 37134077, 2023).
chlamydial infections (1 paper, 2022). "The production of LIF during chlamydial infection has been reported by several in vitro and in vivo studies." (PMID 36329823, 2022). "While this is a protective response in nature, repeated Ct infections and/or persistent Ct infections may lead to aberrant expression of LIF and LIF-mediated alterations of the epithelium, which has been demonstrated in in vitro models of persistent chlamydial infections." (PMID 36329823, 2022).
chorioamnionitis (1 paper, 2024). A morphologic finding indicating inflammation of the fetal sac membranes. "Chorioamnionitis favors multiple pleiotropic cytokines production such as LIF (leukemia inhibitory factor) which is ubiquitously expressed." (PMID 39845245, 2024).
chronic myelogenous leukaemia (1 paper, 2020). "PE‐Ima (LIF, MRGPRF, GRM3, TNNI1 and CACNA2D1) predicted imatinib response in chronic myelogenous leukaemia patients." (PMID 34766125, 2020).
Cirrhosis (1 paper, 2022). A chronic disorder of the liver in which liver tissue becomes scarred and is partially replaced by regenerative nodules and fibrotic tissue resulting in loss of liver function. "ALD-cirrhosis was associated with IL-6, CCL27 and G-CSF and NAFLD-cirrhosis with LIF and CCL25." (PMID 36230823, 2022).
complication (1 paper, 2024). Any disease or disorder that occurs during the course of, or because of, another disease, treatment, or procedure. "Our findings demonstrated that genetically predicted higher levels of IL-12B and LIF likely increased the risk of T1D with renal complications, whereas higher levels of ARTN, CCL28, and S100A12 were related to a decreased risk." (PMID 39040677, 2024).
coronary atherosclerosis (1 paper, 2017). Atherosclerosis of the coronary vasculature. "Regarding LIF (leukemia inhibitory factor), two studies showed that its expression is inversely correlated with coronary atherosclerosis." (PMID 28323859, 2017).
cutaneous melanoma (1 paper, 2015). A primary melanoma arising from atypical melanocytes in the skin. "This indicates that LIF is a major regulator of the TGFβ effects in cutaneous melanoma, not only relaying TGFβ-mediated cell cycle arrest and apoptosis but also TGFβ-mediated cell migration inhibition." (PMID 25885043, 2015).
cyst (1 paper, 2022). A sac-like closed membranous structure that may be empty or contain fluid or amorphous material. "The present study aims to explore the correlation of the transforming growth factor β (TGF-β), drosophila mothers against decapentaplegic protein gene (SMAD) 2/3/4, and leukemia inhibitory factors (LIF) with the cyst formation of hepatic Echinococcus granulosus in young children." (PMID 36443650, 2022). "It is suggested that the TGF-β/Smads/LIF signaling pathway may be present in the process of protoscoleces cyst formation." (PMID 36443650, 2022). "It has been suggested that the TGF-β/Smads/LIF signaling pathway may be present in the process of protoscoleces cyst formation; this provides a research basis for the prevention and treatment of post-infection parasitism of E. multilocularis eggs in young children." (PMID 36443650, 2022).
delirium (1 paper, 2023). A disorder characterized by confusion; inattentiveness; disorientation; illusions; hallucinations; agitation; and in some instances autonomic nervous system overactivity. "Only four proteins were associated with delirium in both age groups: IL-8, IL-6, leukemia inhibitory factor (LIF), and asialoglycoprotein receptor 1 (ASGR1)." (PMID 37156856, 2023). "A few proteins (IL-8, LTBR, TNF-R2 postoperatively; IL-8, IL-6, LIF, ASGR1 by pre- to postoperative change) and 12 networks were common to delirium in both age groups." (PMID 37156856, 2023).
developmental delay (1 paper, 2016). "CNTF and LIF promote oligodendrocyte differentiation in vitro, however, CNTF knockout and LIF knockout mice only have a developmental delay in oligodendrogenesis, indicating that these factors may be a mediator of oligodendrogenesis early in development." (PMID 27895617, 2016).
diabetic nephropathy (1 paper, 2021). "Based on a preliminary scale of clinical urine tests, it was also found that C4b, CXCR6, CFD, and LIF were demonstrated to be biomarker candidates for early detection of diabetic nephropathy." (PMID 33922243, 2021). "The reliability of C4b, CFD, CXCR6, and LIF as a biomarker for detecting diabetic nephropathy was investigated in clinical trials." (PMID 33922243, 2021). "Although LIF has been studied actively in various organs, including kidney, and shows its anti-apoptotic and regulating functions on various cells, there is little information about the effects of LIF on podocyte apoptosis in diabetic nephropathy." (PMID 33922243, 2021). "Further, urinary C4b, CXCR6, CFD, and LIF levels might also potentially be employed as biomarkers to monitor the effectiveness of pharmacological interventions in diabetic nephropathy patients." (PMID 33922243, 2021). "Thus, we selected the complementary complement 4b (C4b), complement factor D (CFD), C-X-C motif Chemokine Receptor 6 (CXCR6), and leukemia inhibitory factor (LIF) as candidate biomarkers for early detection of diabetic nephropathy." (PMID 33922243, 2021). "The urinary levels of C4b, CFD, CXCR6, LIF, KIM-1, and NGAL were markedly increased in diabetic nephropathy patients compared to normal subjects." (PMID 33922243, 2021). "Using diabetic nephropathy models, data demonstrate that urinary levels of C4b, CXCR6, CFD, and LIF were markedly increased compared with conventional biomarkers (KIM-1, NGAL)." (PMID 33922243, 2021).
E. coli infection (1 paper, 2021). "Other studies found that the LPS-induced thymic atrophy during E. coli infection was significantly mediated by leukemia inhibitory factor (LIF, a member of the IL-6 cytokine family) which was able to enhance systemic and intrathymic corticosteroids." (PMID 34113341, 2021).
endometrial tumor (1 paper, 2021). "In this study using endometrial tumor tissue arrays, we identified that expression of LIF, LIFR is upregulated in EC." (PMID 34400617, 2021).
endometrioid adenocarcinoma (1 paper, 2021). An adenocarcinoma characterized by the presence of malignant glandular epithelial cells resembling endometrial cells. "IHC analysis revealed that the expression of LIF and LIFR was significantly greater in the endometrioid adenocarcinoma subtype compared to normal tissues." (PMID 34400617, 2021).
endometritis (1 paper, 2026). An acute or chronic, usually bacterial infectious process affecting the endometrium. "Our findings highlight the therapeutic potential of LIF and OSM as modulators of uterine immune homeostasis and macrophage plasticity modulating and mitigating LPS-acute endometritis and preserving endometrial integrity." (PMID 42256298, 2026).
endotoxemia (1 paper, 2010). "For instance, IL-1, leukemia inhibitory factor (LIF), IFN gamma, and migration inhibitory factor (MIF) may each contribute to the pathogenesis of endotoxemia or septic shock." (PMID 20628562, 2010).
fibrosis (1 paper, 2019). the formation of excess fibrous connective tissue in an organ or tissue in a reparative or reactive process. "Because the CD11b/LIF transgene prevented collagen type 1 accumulation in TA muscles and collagen type 1 is primarily responsible for increased muscle stiffness caused by fibrosis, we assayed for changes in the passive mechanical properties of TA muscles in CD11b/LIF transgenic mdx mice." (PMID 31243277, 2019).
gastritis (1 paper, 2025). Inflammation of the stomach. "Median LIF expression was significantly higher at 1.68 pg/mL in GC patients versus 0.55 pg/mL in gastritis patients, while IL‐11 expression was 0.63 pg/mL in GC patients compared to 0.14 pg/mL in gastritis patients." (PMID 41163398, 2025). "H. pylori load, LIF, and IL‐11 were significantly higher in GC patients than in gastritis patients." (PMID 41163398, 2025).
genital herpes (1 paper, 2025). Herpes simplex infection of the genitals, most commonly caused by the herpes simplex-2 virus. "PBMC from HSV-2 meningitis patients secreted higher levels of several Th1 (IFN-γ) and inflammatory cytokines (IL-6, LIF, IL-8) in response to HSV-2 compared to PBMC from HSV-2 genital herpes patients." (PMID 40534882, 2025).
Glucose intolerance (1 paper, 2017). Glucose intolerance (GI) can be defined as dysglycemia that comprises both prediabetes and diabetes. "Another remarkable outcome of the inhibition of hypothalamic LIF was the generation of glucose intolerance." (PMID 28865476, 2017).
gynecological cancers (1 paper, 2022). "While there are a multitude of studies that highlight the role of LIF in gynecological and reproductive physiology, there is a comparative lack of studies of potential roles of LIF in gynecological cancers." (PMID 35204717, 2022).
HIV-1 infection (1 paper, 2022). The type species of lentivirus and the etiologic agent of acquired immunodeficiency syndrome (AIDS). "It is more likely, though, that miR-223 influences HIV-1 infection by targeting cellular factors required for replication, such as ras homolog family member B (RhoB), Sp3 transcription factor (Sp3), and leukemia inhibitory factor (LIF)." (PMID 36142450, 2022). "LIF can restrict HIV-1 replication, and has been reported to be down-regulated in early HIV-1 infection." (PMID 36142450, 2022). "This miRNA may also function as a positive factor in HIV-1 infection by targeting HIV-1-suppressive Sp3 and LIF." (PMID 36142450, 2022).
hydatidosis (1 paper, 2022). "The expression levels of TGF-β, SMAD2, SMAD3, SMAD4, and leukemia inhibitory factors (LIF) in the cystic fluid and the corresponding paracystal tissues of infected viscera or tissues in children with hydatidosis were measured using the ELISA kit." (PMID 36443650, 2022).
hyperandrogenism (1 paper, 2024). Excessive secretion of androgens from the adrenal glands or gonads. "Thus, various signaling pathways such as hyperandrogenism, LIF, and insulin resistance are disrupted in PCOS, leading to impaired endometrial receptivity." (PMID 38256276, 2024). "The hormonal imbalances in PCOS, particularly hyperandrogenism and altered LH/FSH ratios, disrupt the endometrial cycle, leading to decreased levels of progesterone and leukemia inhibitory factor (LIF), both crucial for endometrial receptivity and implantation." (PMID 38256276, 2024).
hypothyroidism (1 paper, 2025). Abnormally low levels of thyroid hormone. "On the other hand, rats with hypothyroidism show reduced endometrial gland development, lower uterine expression of LIF, and reduced implantation rates." (PMID 39859259, 2025). "Additionally, hypothyroidism led to reduced uterine gene expression of LIF, BMP2, WNT4, and HAND2." (PMID 39859259, 2025).
infarction (1 paper, 2024). A localised pathological necrosis of tissue resulting from obstruction of the blood supply usually by a thrombus, an embolus, or vascular torsion. "Notably, this study also demonstrated that LIF promotes angiogenesis and suppresses inflammation in the peri-infarct region, thereby improving post-infarction ventricular remodeling." (PMID 39726944, 2024).
intestinal tumor (1 paper, 2023). "We conducted an analysis of LIF secretion in GC cell lines previously characterized and classified as diffuse or intestinal tumor types." (PMID 38137514, 2023).
ischemic disease (1 paper, 2020). Lack of blood supply to an area of the body, resulting in impairment of tissue oxygenation. "In conclusion, LIF overexpression is a promising strategy to increase the proangiogenic potential of MSCs and sets precedents for future investigations of their potential applications for the treatment of ischemic diseases and tissue repair." (PMID 32923442, 2020).
ischemic heart diseases (1 paper, 2021). "The prophylactic and long-term design of most delivery approaches to enhance OSM and LIF signaling in rodents additionally did not permit a reliable prognosis of their therapeutic potential for the treatment of acute ischemic heart diseases." (PMID 35008777, 2021).
ischemic optic neuropathy (1 paper, 2013). "In both ischemic optic neuropathy and IOP elevation animal models, alterations of LIF, IL-6 and other JAK-STAT signaling pathway components in the optic nerve have been reported." (PMID 23383263, 2013).
joint disease (1 paper, 2019). "Genetic manipulation of the IL-6/leukemia inhibitory factor (LIF) cytokine axis through sustained activation of gp130 in mice (gp130-KI mice/gp130ΔSTAT/ΔSTAT), causes severe joint disease with features representative of RA, and interestingly, GI ulceration." (PMID 31847438, 2019).
keloid (1 paper, 2024). An irregularly shaped, elevated mark on the skin caused by deposits of excessive amounts of collagen during wound healing. "In summary, the present study provides novel immune signatures (PTGFR, RBP5, and LIF) for keloid diagnosis and treatment, and identifies retinoic acid as potential anti-keloid drugs." (PMID 39014455, 2024). "The results of qRT-PCR showed that KHIGs had significant differences in keloid fibroblast samples (p value ≤ 0.05), and LIF expression was up-regulated in keloid." (PMID 39014455, 2024). "In conclusion, the present study provided new immune signatures (PTGFR, RBP5, and LIF) for keloid diagnosis and treatment using multiple bioinformatic analyses and machine learning algorithms." (PMID 39014455, 2024). "LIF was significantly up-regulated in keloids compared to normal skin, while PTGFR and RBP5 were down-regulated in keloids." (PMID 39014455, 2024).
Lassa fever (1 paper, 2024). A viral hemorrhagic fever that is caused by the Lassa virus, which is transmitted by contact with infected rodents; it is characterized by fever, headache, malaise, myalgia, and hearing loss. "GWAS in difficult-to-recruit populations identifies variants associated with Lassa fever outcome and susceptibility at loci proximal to LIF, GRM7 and LARGE1." (PMID 38326571, 2024). "We find that an intronic variant within GRM7 and a variant downstream of LIF are significantly associated with Lassa fever in the Nigeria cohorts and meta-analysis of the two cohorts, respectively." (PMID 38326571, 2024).
malignant peripheral nerve sheath tumor (1 paper, 2021). Malignant peripheral nerve sheath tumor (MPNST) is a rare and often aggressive soft tissue sarcoma occurring in a wide range of anatomical sites. "Notably, a previous study examined the effects of LIF on sNF96.2, Schwann cells collected from malignant peripheral nerve sheath tumor, and found that LIF inhibits the proliferation but enhances the migratory capacity of sNF96.227." (PMID 33888681, 2021).
meningitis (1 paper, 2025). A disorder characterized by acute inflammation of the meninges of the brain and/or spinal cord. "We thus confirm previous studies showing enhanced IFN-γ production by PBMC from meningitis patients and show that the HSV-2-induced production of several other cytokines, i.e. IL-6, LIF and IL-8, are produced to a higher degree in PBMC from meningitis patients." (PMID 40534882, 2025). "The IFN-γ and LIF (but not IL-6 and IL-8) responses to HSV-2 antigen were also higher in PBMC from meningitis patients, indicating that these two cytokines represented recall responses." (PMID 40534882, 2025).
meningoencephalitis (1 paper, 2018). Inflammation of the meninges and brain, generally secondary to an infectious cause. "In addition, CV-B4 infections, which are mainly associated with meningoencephalitis, neonatal myocarditis and type-1 diabetes, can also promote cytokine and chemokine production in host cells (e.g., IL-6, LIF, and GM-CSF)." (PMID 30545363, 2018).
metastasis (1 paper, 2025). The spread or migration of cancer cells from one part of the body (where they first appeared) to another. "Clinically, high LIF expression is associated with poor prognosis, peritoneal metastasis, and resistance to chemotherapy and immunotherapy." (PMID 41163398, 2025).
migraine (1 paper, 2017). "Up-regulation of LIF, a mast cell growth-enhancing factor, in mutation carriers further supports the role of mast cells in migraine pathogenesis." (PMID 28900389, 2017). "Cytokines CXCL1, HGF, and LIF appear to be also higher in at least one patient with migraine with aura." (PMID 28900389, 2017). "LIF also promotes the growth of mast cells, which are considered to play a triggering role in pathogenesis of migraine." (PMID 28900389, 2017).